PIM1 (Pim-1 proto-oncogene, serine/threonine kinase)
Diseases named in the same sentence as PIM1 in open-access papers (continued):
Sharing a sentence is not in itself a finding about the gene and the disease.
prostate carcinoma (continued). "However, few studies investigated the impact of PIM1 on autophagy and radioresistance of prostate cancer." (PMID 26990493, 2016). "Additionally, PIM-1 promoted prostate cancer cell migration and invasion by phosphorylating CXCR4 at Ser‐339." (PMID 27596051, 2016). "Also, depletion of Pim-1 by RNA interference in mouse and human prostate cancer cells reduced cellular proliferation and survival." (PMID 25121590, 2014). "In accordance with this last hypothesis it has been published that PIM1-dependent phosphorylation of AR impacts in gene transcription and is prevalent in aggressive prostate cancer." (PMID 23565217, 2013). "However, more recently Pim1 was found to be increased in solid tumors, including pancreatic and prostate cancers, and has been proposed as a prognostic marker." (PMID 23565217, 2013). "In prostate cancer, the expression of PIM-1 transcripts is related to the grade of prostate carcinomas; higher PIM-1 expression is associated with higher WHO grades and higher Gleason scores, while upregulation of PIM-1 is related to the progression to a more aggressive form of prostate carcinoma." (PMID 23115625, 2012). "Since it has previously been observed that PIM1 over-expression can exert a pro-survival activity in prostate cancer cells treated with chemoterapeutic drugs, we tried to assess whether this phenomenon can be observed also in the non-tumoral RWPE-1 model." (PMID 22140532, 2011). "PIM1 expression is known to be elevated in approximately 50% of prostate cancer cases." (PMID 22140532, 2011). "The slower recovery of RWPE-1_tERG cells after treatment with chemotherapeutic drugs, prompted us to investigate whether the tERG/PIM1 axis could affect genetic stability in early phases of prostate cancer progression." (PMID 22140532, 2011). "Pim1 has been reported to modulate androgen receptor signaling in prostate cancer cells." (PMID 20515470, 2010). "Our finding that 10058-F4, a small molecule c-Myc inhibitor could target both Pim1 protein expression and c-Myc transcriptional activity in both androgen-dependent and -independent prostate cancer cells is intriguing and of potential clinical significance." (PMID 20515470, 2010). "However, there has been limited analysis of the tumorigenic potential of Pim1 overexpression in benign and malignant human prostate cancer cells in vivo." (PMID 20515470, 2010). "We next asked whether Pim1 can enhance the tumorigenicity of established malignant prostate cancer cells." (PMID 20515470, 2010). "In human prostate cancer, whether PIM1 plays a role in tumor initiation and/or tumor progression has not been clearly defined." (PMID 20515470, 2010). "Since Pim1 and c-Myc cooperate to promote the development of lymphoma and prostate cancer, targeting both molecules with one drug could dramatically enhance the efficacy of the treatment in cancer patients." (PMID 20515470, 2010). "However, Pim1 expression enhanced the in vitro and in vivo tumorigenic potentials of the human prostate cancer cell lines LNCaP and DU145." (PMID 20515470, 2010). "Inhibition of Pim-1 results in a significant growth repression of prostate cancer cell." (PMID 21143989, 2010). "In prostate cancer, the expression of the PIM1 protein has been shown to correlate with clinical outcome, and the novel detection of this proto-oncogene in carcinoid tumour cells warrants further studies to explore its role as a potential prognostic marker also in NE GI tumours." (PMID 15846300, 2005). "Thus, identifying a signaling target linked to lipid metabolism downstream of GSK3β inhibition could be insightful for uncovering the mechanism by which PIM1 mediates LD accumulation in prostate cancer." (PMID 38097734, 2024).
prostate carcinoma (continued). "The flavonol myricetin could suppress the CXCL12-CXCR4 axis in human prostate cancer cells PC-3 via inhibiting the activity of Moloney murine leukemia virus 1 (PIM1) and disrupting its interaction with CXCR4, leading to a significant decrease in CXCL12-induced cell migration." (PMID 39465008, 2024). "Given that LD accumulation in our experimental setting occurred through the GSK3β-PPARα signaling axis downstream of PIM1, we hypothesized that blocking PPARα could counteract the known positive effect of PIM1 induction on cell proliferation in prostate cancer." (PMID 38097734, 2024). "Finally, we investigated whether the effects of PIM1 on LD accumulation are replicated in vivo using a xenograft model of prostate cancer." (PMID 38097734, 2024). "In addition, PIM-1 is essential in activating the NF-κB pathway, which allows for the survival of prostate cancer cells treated with docetaxel, whereas PIM-1 knockdown or expression of a dominant negative protein sensitizes cells to the cytotoxic effects of docetaxel." (PMID 37514177, 2023). "However, to date, the role of PIM1 in the development and maintenance of GSCs has not been described, although PIM1 signaling pathways are associated with cancer stem cells in prostate cancer." (PMID 34681783, 2021). "Furthermore, PIM1 has been observed to enhance MYC‐induced tumorigenicity in human PCa in a mouse xenograft model, while coexpression of PIM1 and MYC in human PCa is associated with higher Gleason scores, suggesting that these oncoproteins synergize to induce advanced prostate carcinoma." (PMID 33932111, 2021). "Moreover, Pim-1 is related to various cancers, e.g. prostate carcinomas." (PMID 28467776, 2017). "Therefore, hypoxia induced miR‐124 and miR‐144 downregulation may contribute to a prosurvival mechanism of prostate cancer cells to hypoxia and irradiation at least through attenuated suppressing of PIM1." (PMID 26990493, 2016). "In addition, PIM1 may also exert protective effect on prostate cancer cells to chemotherapeutic drugs." (PMID 26990493, 2016). "This hypothesis could explain the results of Wang and colleagues showing that Pim1 depletion by RNA interference in mouse and human prostate cancer cells decreased cellular proliferation, survival, Erk signaling and tumorigenicity even when MYC levels were not significantly altered." (PMID 23565217, 2013). "Fucoxanthin also induces G1 phase arrest in HepG2 (liver cancer) and DU145 (prostate cancer) cell lines by the induction of the expression of GADD45α, GADD153 and proto-oncogene serine/threonine-protein kinase Pim-1 (PIM1)." (PMID 39334719, 2024). "SGI-1776, the first PIM-1 inhibitor that targets all three PIM kinases, has been tested in clinical trials in non-Hodgkin lymphoma and prostate cancer patients." (PMID 36243702, 2022). "Therefore, these substrates may be the most representative of PIM1 activity in prostate cancer." (PMID 33398037, 2021). "We next probed a panel of prostate cancer cell lines for NDRG1 pS330, total NDRG1, and PIM1 by western blot." (PMID 33398037, 2021). "In light of these findings, and given the previously demonstrated ability of PIM1 to promote cell migration and invasion, we investigated the effect of NDRG1 phosphorylation on the migration and invasion of prostate cancer cells." (PMID 33398037, 2021). "To do this, we treated two unrelated AR-positive prostate cancer cell lines, LAPC4 and 22RV1, with the PIM1 inhibitor SGI-1776." (PMID 34697370, 2021). "Subsequently, Pim1 increased the RTK protein expression, including EGFR, HER2, and HER3 through Cap-independent translation, resulting in the resistance of prostate cancer cells to AKT inhibition." (PMID 34267653, 2021). "PIM-1 is regulated by STAT3 and is overexpressed in high-grade prostatic intraepithelial neoplasia and is overexpressed in 50% of human prostate cancers." (PMID 34439133, 2021).
prostate carcinoma (continued). "While PIM1 and PIM2 levels are mostly elevated in hematologic malignancies and prostate cancer, increased PIM3 expression is typically observed in other solid tumors." (PMID 32504181, 2020). "PIM1, in turn, was shown to enhance the growth of lung adenocarcinoma by potentiating the c-MET signaling pathway and the growth of prostate carcinoma and triple-negative breast cancer in cooperation with MYC." (PMID 32504181, 2020). "We used mass spectrometry to identify PIM1 phosphorylation target sites in NFATC1, and analysed their functional roles in three prostate cancer cell lines by comparing phosphodeficient mutants to wild-type NFATC1." (PMID 31730483, 2019). "In conclusion, we have shown that phosphorylation of PIM1 target sites stimulates the transcriptional activity of NFATC1 and enhances its ability to promote prostate cancer cell migration and invasion." (PMID 31730483, 2019). "We also performed a microarray analysis to identify novel PIM1/NFATC1 targets, and validated one of them with both cellular expression analyses and in silico in clinical prostate cancer data sets." (PMID 31730483, 2019). "Based on our data, phosphorylation of PIM1 target sites stimulates NFATC1 activity and enhances its ability to promote prostate cancer cell migration and invasion." (PMID 31730483, 2019). "PIM-1 increases the phosphorylation of ABCG2 at Thr362, and downregulation of PIM-1 increases the chemosensitivity of prostate cancer cells." (PMID 27596051, 2016). "PIM1 is weakly oncogenic in naive adult mouse prostatic epithelium, however, it synergizes with c-MYC to induce prostate cancer within 6-weeks." (PMID 23565217, 2013). "To further validate these effects on LDs, we generated PC3LN4 prostate cancer cells lacking PIM1 (PC3LN4crisprPIM1) or stably overexpressing PIM1 (PC3LN4hPIM1)." (PMID 38097734, 2024). "Using pull-down, co-immunoprecipitation, and intracellular Ca2+ flow tests, myricetin selectively inhibited Moloney murine leukaemia virus-1 (PIM1) and disrupted the link between PIM1 and CXCR4 to have cytotoxic, pro-apoptotic, and anti-metastatic effects on prostate cancer cells." (PMID 38496846, 2024). "PC3-LN4 prostate cancer cells lacking PIM1, which display higher GSK3β activation, show a significant decrease in genes linked to peroxisomal biogenesis (peroxisomal biogenesis factor 3 and 5; PEX3 and PEX5) and LD growth (Tip47)." (PMID 38097734, 2024). "PIM1 plays a critical role in the development of many hematopoietic and non-hematopoietic malignancies, including prostate cancer and acute myeloid leukemia." (PMID 36479666, 2023). "The data show that overexpression of CK2 and PIM-1 kinases is a poor predictor in many cancers, such as prostate cancer and breast cancer, among others, and the reduction in CK2 and PIM-1 activity by chemical or molecular methods induces apoptosis in tumor cells." (PMID 37514177, 2023). "While PIM1 protein levels are elevated in prostate cancer relative to local disease, the mechanisms by which PIM1 contributes to oncogenesis have not been fully elucidated." (PMID 33398037, 2021). "We have chosen to study PIM-1, since very recent data have shown that PIM-1 kinase plays a critical role in tumorigenesis, and overexpression of PIM-1 protein has been suggested as a potential biomarker for many malignancies including prostate cancer." (PMID 32397108, 2020). "Here we have identified ten PIM1 target sites in NFATC1 and found that prevention of their phosphorylation significantly decreases the transcriptional activity as well as the pro-migratory and pro-invasive effects of NFATC1 in prostate cancer cells." (PMID 31730483, 2019). "Early efforts focused on PIM1 specifically, and a compound with potent PIM1 inhibitory activity, SGI-1776, entered phase 1 clinical evaluation for patients with relapsed or refractory prostate cancer or lymphoma in 2008." (PMID 27556513, 2016).
prostate carcinoma (continued). "In addition, Pim-1 has been shown to regulate the CXCR4/CXCL12 chemokine pathway, which plays an important role in migration and invasion of both leukemic and prostate cancer cells." (PMID 26075720, 2015). "To gain further insights into the role of tERG-mediated PIM1 induction in prostate cancer progression, we stably over-expressed tERG in the non-tumorigenic prostate epithelial cell line RWPE-1." (PMID 22140532, 2011). "Our findings that Pim1 expression could significantly promote tumorigenicity in established human prostate cancer cell lines (LNCaP and DU145) indicate a clear role for Pim1 in tumor progression." (PMID 20515470, 2010). "PIM1, a serine/threonine protein kinase, can directly bind to CXCR4 and facilitate its membranous expression, whereas the elevated co-expression of these two proteins, PIM1 and CXCR4, was correlated with aggressiveness and poor prognosis in prostate cancer patients." (PMID 39465008, 2024). "Overall, these results indicated that pim1 may not be sufficient to promote the onset of invasive prostate cancer but suggested that pim1 expression may be necessary for maintaining Erk signaling and, therefore, prostate cancer cell tumorigenicity." (PMID 24860787, 2014). "Furthermore, targeting Pim-1 sensitized prostate and colon cancer cells to chemotherapeutic agents, and improved the efficacy of AKT inhibitors and epidermal growth factor receptor (EGFR) targeted therapies in prostate cancer." (PMID 25342548, 2014). "Some studies have found absent or weak expression of PIM1 in most high-grade prostatic intraepithelial neoplasia (HGPIN) lesions, the putative precursor lesion for prostate cancer, consistent with a role for PIM1 in tumor progression, rather than tumor initiation." (PMID 20515470, 2010). "However, the oncogenic activity of Pim1 itself in prostate cancer using in vivo models has not been fully characterized." (PMID 20515470, 2010). "Thus, the effects of PIM1 on LD in prostate cancer are independent of AR or PTEN." (PMID 38097734, 2024). "Here we show positive correlations between PIM1 and either CAPZA1, CAPZA2 or CAPZB mRNAs in prostate cancer samples with different Gleason grades, but not in the healthy control tissues." (PMID 32771000, 2020). "There are clinical trials to explore the safety of one of the Pim-1 inhibitor, SGI-1776, for the treatment of refractory non-Hodgkin's lymphoma and prostate cancer." (PMID 21143989, 2010). "Additionally, in prostate cancer (DU45) and pancreatic cancer (MiaPaCa-2) cell lines, PIM3 specifically, but not PIM1 and PIM2, regulates p-STAT3 levels, potentially through its protein tyrosine phosphatase and tyrosine kinase activity." (PMID 38339286, 2024). "While no clear PIM-dependent changes in integrin activity or expression have previously been reported, we now found correlations between PIM1 or NFATC1 mRNA expression levels with ITGA5, both in PC-3 cells and in prostate cancer patient-derived samples." (PMID 31730483, 2019). "Interestingly, the hormone-independent prostate cancer cell lines PC-3 and DU-145 behave quite similarly, while no major phosphorylation-dependent changes are detected in the androgen-dependent LNCAP cells with relatively low PIM1 levels." (PMID 32771000, 2020). "In contrast to pim1 grafts, all of the c-myc and c-myc/K67M grafts showed multiple foci of high-grade prostate intraepithelial neoplasia (PIN), a putative precursor lesion for prostate carcinoma, but none of them showed evidence of invasive cancer after 42 days." (PMID 24860787, 2014).
lymphoma (48 papers, 2004 to 2025). A malignant (clonal) proliferation of B- lymphocytes or T- lymphocytes which involves the lymph nodes, bone marrow and/or extranodal sites. "Within COSMIC, Ser97 is the position in PIM1 with the most missense variants, of which 37 are p.Ser97Asn, and all in haematopoietic and lymphoid cancers." (PMID 41152984, 2025). "PCNSL and SCNSL were expected to be very similar as both need to adapt to the CNS environment; only MYD88 and PIM1 mutations and lymphoma translocations showed differing abundances." (PMID 40346678, 2025). "Mutations in the PIM1 gene are frequently seen in lymphomas and have been implicated in DLBCL pathogenesis." (PMID 38914869, 2024). "The use of Pim-1 and Pim-2 expressing lymphoid cells in transgenic mice also causes a low frequency of lymphomas after long latency periods; whereas Pim-3 expressing liver cells of transgenic mice produce carcinomas but only in the presence of carcinogens." (PMID 36694243, 2023). "In conjunction with their cellar distribution, Pim-1 transgenic mice are susceptible to lymphomas; and Pim kinases have roles in the differentiation, activation, and/or response of immune cells." (PMID 36694243, 2023). "Several studies have shown that PIM-1 expression can be found in various lymphomas, and its high expression is associated with a poor prognosis." (PMID 36871027, 2023). "This assay showed that Eμ-Pim1 mice are highly susceptible to X-ray-induced lymphoma and thus susceptible to carcinogens that act directly to induce large chromosomal deletions and rearrangements rather than point mutations." (PMID 24860787, 2014). "Because Eμ-pim1 mice are 25-fold more susceptible to ENU-induced lymphoma, this mouse model seemed to be useful to test a variety of other carcinogens." (PMID 24860787, 2014). "Like Pim-1 the over-expression of Pim-2 in transgenic mice predisposes the mice to the development of lymphoma." (PMID 16403219, 2006). "The high frequency of mutations in PIM1 compared with other lymphomas may have implications in the clinical presentation and evolution of this type of lymphoma." (PMID 29262531, 2017). "By contrast, neither of these mechanisms has yet been implicated in the regulation of the PIM1 gene, although prolactin activates its transcription in a lymphoma model through several proximal upstream promoter elements, and also requires activation of the Akt kinase." (PMID 22413002, 2012). "Our results show a higher frequency of mutations in PIM1 (50%) compared with other lymphomas of nodal (12–30%) or extra-nodal origin (22–25%), which may have implications in the clinical presentation and course of this type of lymphoma." (PMID 29262531, 2017). "PIM2 is expressed in myeloma, lymphoma, and leukemia, whereas PIM1 is detected in many types of solid tumors and blood cancers." (PMID 38339286, 2024). "Early studies of the original Pim kinase, Pim-1, led to the discovery of an oncogenic role for the Pim kinase family in lymphoma." (PMID 36694243, 2023). "Among them, high expression levels of PIM1 and PIM2 were more common in DLBCL, which were associated with active STAT signaling, lymphoma proliferative activity, and higher disease stage." (PMID 36871027, 2023). "PIM1 was found to be highly expressed in various tumors, including lymphoma, leukemia, bladder cancer, and prostate cancer." (PMID 36871027, 2023). "In diffuse large B-cell lymphoma, SNHG16 was shown to sponge miR-497-5p, releasing PIM1 from miR-497-5p-mediated inhibition, which promotes proliferation, cell cycle and inhibits apoptosis of lymphoma cells." (PMID 35740344, 2022).